RNU6-932P (RNA, U6 small nuclear 932, pseudogene)
Gene: Small nuclear RNA gene on chromosome 2 (157,985,789 to 157,985,894, reverse strand). Ensembl gene ENSG00000212410.
Homologues: Orthologues: chimpanzee U6 (100% identical), macaque U6 (98% identical), pig U6 (87% identical), dog U6 (80% identical), guinea pig U6 (66% identical), rabbit U6 (66% identical), rat LOC120097200 (62% identical), mouse Gm22699 (61% identical), rabbit U6 (60% identical). Paralogues in human: RNU6-317P (85% identical), RNU6-1122P (84% identical), RNU6-41P (83% identical), RNU6-1011P (82% identical), RNU6-1060P (82% identical), RNU6-15P (82% identical), RNU6-19P (82% identical), RNU6-48P (82% identical), RNU6-530P (82% identical), RNU6-1042P (81% identical), RNU6-10P (81% identical), RNU6-1103P (81% identical), and 1284 more.